BDNF (brain derived neurotrophic factor)
Diseases named in the same sentence as BDNF in open-access papers (continued):
Sharing a sentence is not in itself a finding about the gene and the disease.
acute coronary syndrome (25 papers, 2010 to 2026). Signs and symptoms related to acute ischemia of the myocardium secondary to coronary artery disease. "This study investigated the potential modifying effects of the level of the serum interleukin-18 (IL-18) on the association between BDNF methylation status and long-term cardiovascular outcomes in patients with acute coronary syndrome (ACS)." (PMID 36499595, 2022). "The prognostic role of BDNF val66met polymorphism on long-term cardiac outcomes in acute coronary syndrome (ACS) has been unclear." (PMID 31887219, 2019). "For example, reduced plasma or serum levels of BDNF were noted in patients with increased risk of stroke, with chronic heart failure or with acute coronary syndromes." (PMID 31341469, 2019). "A lower CpG methylation level within the regulatory domain of the Bdnf gene is related to increased BDNF synthesis in neurons, and a higher BDNF methylation level has been linked to composite major adverse cardiac events (MACEs) in patients with acute coronary syndrome (ACS)." (PMID 36499595, 2022). "Besides the fundamental impact on the nervous system, several reports documented an association between plasma BDNF and systemic or peripheral inflammatory conditions, such as acute coronary syndrome and T2DM." (PMID 29062839, 2017). "Patients with acute coronary syndrome (ACS) showed reduced circulating levels of BDNF compared with control subjects in a cross-sectional study." (PMID 36741831, 2022). "This study investigated the potential modifying effects of the serum brain-derived neurotrophic factor (sBDNF) level on the association between BDNF methylation status and long-term cardiovascular outcomes in acute coronary syndrome (ACS) patients." (PMID 36741831, 2022). "In a small case-control study conducted in 19 healthy controls and 31 patients with acute coronary syndrome, lower BDNF concentration was observed in patients compared with controls, indicating BDNF perhaps has a role of cardiovascular protection." (PMID 26758679, 2016). "In acute coronary syndromes, ischemic tissues contain increased BDNF levels that correlate with inflammation and oxidative stress whereas serum levels are decreased." (PMID 21085492, 2010). "Moreover, larger patient cohort studies comparing BDNF level expression in PE patients, as well as in patients with other acute chest syndromes, such as acute coronary syndrome, COPD, pulmonary infections, and aortic dissections, are mandatory." (PMID 36078878, 2022). "However, the ability of BDNF to modify fibrin clot structure suggests its clinical relevance as a potential biomarker of thrombosis including acute coronary syndrome (ACS)." (PMID 35911513, 2022). "Decreased BDNF concentrations have been observed in acute coronary syndrome." (PMID 21085492, 2010). "Moreover, BDNF expression is significantly increased in atherosclerotic coronary arteries, compared to nonatherosclerotic coronary arteries from control subjects, and one study has demonstrated that there are reduced plasma BDNF levels in patients with acute coronary syndromes." (PMID 20404913, 2010).
spinal cord injury (25 papers, 2008 to 2025). Penetrating and non-penetrating injuries to the spinal cord resulting from traumatic external forces (e.g., WOUNDS, GUNSHOT; WHIPLASH INJURIES; etc.). "BDNF-TrkB signaling is associated with the modulation of pain perception, nociceptive plasticity, and spinal learning after cervical spinal cord injury." (PMID 39000303, 2024). "P-value 5.05 × e10-48) and spinal cord injury (WikiPathways 2024 Human, BDNF Spinal Cord Injury WP2431, adj." (PMID 40308216, 2025). "Docosahexaenoic acid administration normalised BDNF in the hippocampus, increased the growth of uninjured corticospinal and serotonergic fibres, and enhanced synaptic plasticity in an animal model of spinal cord injury." (PMID 28218722, 2017). "Neuroplasticity implications: While no studies explicitly link spinal cord perfusion pressure (SCPP) to BDNF/TrkB signaling, several investigations highlight BDNF/TrkB’s critical role in promoting axonal sprouting within corticospinal tracts after spinal cord injury (SCI)." (PMID 40278428, 2025). "Nonetheless, certain studies have discovered that diminished BDNF levels, rather than increases, are linked to functional impairments and heightened mechanical sensitivity following spinal cord injury (SCI)." (PMID 38368171, 2024). "An in vivo study conducted on dogs demonstrated that post-spinal cord injury (SCI) transplantation of ADMSCs overexpressing BDNF (BDNF-ADMSC) and ADMSCs overexpressing heme oxygenase-1 (HO1-ADMSC) significantly contributed to functional recovery, inflammation reduction, and restoration." (PMID 38004615, 2023). "Furthermore, interventions that increase signaling through BDNF and/or its receptor TrkB markedly improve recovery of diaphragm function following cervical spinal cord injury." (PMID 27588166, 2016). "We aimed to investigate whether an innovative growth factor-laden scaffold composed of acellular sciatic nerve (ASN) and brain-derived neurotrophic factor (BDNF) could promote axonal regeneration and functional recovery after spinal cord injury (SCI)." (PMID 22952613, 2012). "Research has extended to examine how spinal cord injury (SCI) influences BDNF plasticity and the effects BDNF has on sensory and motor functions after SCI." (PMID 27721996, 2016). "It has been suggested that upregulation of GAL expression in DRG neurons in micturition pathways after spinal cord injury (SCI) may be mediated by changing neurotrophic factors expression such as NGF and brain-derived neurotrophic factor (BDNF)." (PMID 34948196, 2021). "Interestingly, increased levels of BDNF, NGF, and NT-3 in the injured spinal cord may be the main therapeutic effect of using hUCB-MSCs to treat spinal cord injuries (SCI)." (PMID 37185735, 2023). "Similarly, after spinal cord injury (SCI), the level of BDNF also gradually increased with partial functional restoration, and BDNF overexpressing facilitated the recovery of locomotor function, while BDNF knockdown wound led to opposite outcome." (PMID 30766469, 2018). "However after spinal cord injury (SCI), BDNF's actions appear to be more complex." (PMID 27721996, 2016). "However, a study on people with spinal cord injury (SCI) found that acute submaximal exercise did not impact plasma or serum BDNF levels or cognitive function, suggesting that the relationship between exercise intensity and BDNF in individuals with CI may be more complex." (PMID 38393277, 2024).
angina pectoris (24 papers, 2011 to 2024). The symptom of paroxysmal pain consequent to MYOCARDIAL ISCHEMIA usually of distinctive character, location and radiation. "Low plasma BDNF levels are associated with coronary events and mortality in patients with angina pectoris." (PMID 38859660, 2024). "Low levels of BDNF have been reported in patients with acute coronary syndrome and in association with increased incidence of coronary events in Chinese patients with angina pectoris." (PMID 26161003, 2015). "A previous study investigating the relationship between unstable angina and the BDNF Val66Met polymorphism similarly identified a protective effect of the Met/Met genotype." (PMID 21437208, 2011). "This functional polymorphism was recently found to be associated with unstable angina, supporting a genetic basis for the BDNF-vascular interaction." (PMID 21437208, 2011). "Furthermore, various risk factors for cardiovascular diseases have been identified as independent determinants of low plasma BDNF levels in patients with angina, and reduced plasma BDNF may be associated with future coronary events and mortality." (PMID 39648800, 2024). "We found that serum BDNF significantly decreased after the intake of 75 g of glucose in adult patients with angina." (PMID 32679912, 2020). "For instance, low plasma levels of BDNF were found to be an independent predictor of a major coronary event in a Chinese cohort of patients with angina pectoris." (PMID 26161003, 2015). "On the other hand, plasma BDNF levels show a negative association with the fibrinogen level in patients with angina pectoris." (PMID 37712092, 2023). "Here, we aimed at assessing whether plasma BDNF levels are associated with coronary plaque features in AMI patients and in those with stable angina (SA), with the goal of pinpointing high-risk patients and vulnerable rupture-prone coronary plaques." (PMID 34205863, 2021). "Third, different coronary BDNF expression had been reported between stable and unstable angina." (PMID 30424498, 2018). "Circulating BDNF levels reportedly can predict survival in patients with angina." (PMID 30424498, 2018). "Therefore, in the present study, we aimed to assess serum renalase levels before and after PCI in CAD patients with angina and examined the relationship of BDNF levels with the change in serum renalase levels." (PMID 30424498, 2018). "In contrast, higher BDNF level was found in patients with unstable angina compared with individuals with stable angina, suggesting that BDNF may play an important role in atherogenesis and plaque instability." (PMID 26758679, 2016). "Though the pathogeneses of RCVS and unstable angina might differ, the common findings of both studies suggest the benefit of further BDNF studies in vascular disorders." (PMID 21437208, 2011). "High BDNF levels play a protective role against CVD and CVD-related mortality, whereas low serum BDFN levels are considered a risk factor for future coronary events and are associated with an increase in risk of future coronary events and mortality in patients with angina." (PMID 37895349, 2023).
diabetic retinopathy (24 papers, 2011 to 2025). "BDNF is one of the nerve growth factor family members and is associated with the pathogenesis of diabetic retinopathy and one of the therapeutic options." (PMID 35010703, 2021). "It was proved that a low serum level of BDNF was a risk factor for diabetic retinopathy." (PMID 32012942, 2020). "This study shows that a low serum level of BDNF is a risk factor for diabetic retinopathy." (PMID 32012942, 2020). "In particular, under high-glucose conditions mimicking the environment of diabetic retinopathy, MCs treated with BDNF showed suppressed NF-κB protein expression while treatment with BDNF siRNA had the opposite effect." (PMID 35955747, 2022). "NEAT1 treatment suppressed the apoptosis of retina Müller glial cells after diabetic retinopathy through modulating miR-497/BDNF cascade (by downregulating miR-497 and upregulating BDNF)." (PMID 33374507, 2020). "Brain-derived neurotrophic factor and the vascular endothelial growth factor have pivotal roles in the pathogenesis of diabetic retinopathy." (PMID 32509339, 2020). "NCF1, OSM, SMAD1 and TGFB1 provide protection against diabetic nephropathy, SYVM1 and TXNIP protect against diabetic retinopathy and BDNF in ameliorating the diabetic neuropathy." (PMID 28761062, 2017). "Although many studies have described the important roles of BDNF in the physiology and pathophysiology of the retina, few studies have examined the changes of BDNF levels or activity in models of diabetic retinopathy." (PMID 21293735, 2011). "This article explores the neuroprotective potential of BDNF in the management of diabetic retinopathy, emphasizing its role in mitigating neuronal and vascular damage, aiming to uncover novel pathways for preserving vision and addressing the complex pathophysiology of DR." (PMID 40003672, 2025). "It has been demonstrated that BDNF and VEGF levels show similar dynamics in preterm infants with ROP, and that BDNF might be involved in the development of diabetic retinopathy." (PMID 39529072, 2024). "MG migration was studied in response to concentration gradients of EGF and VEGF, two key factors for diabetic retinopathy, while ShC migration was examined in response to gradients of BDNF, critical to nerve regeneration and guidance in peripheral neuropathies." (PMID 31370352, 2019). "Thus, the optimal concentration of BDNF should be found for the treatment of diabetic retinopathy." (PMID 35010703, 2021). "Thus, the serum level of BDNF can be an indicator of the progression of diabetic retinopathy." (PMID 35010703, 2021). "BDNF could be a possible serum biomarker of diabetic retinopathy." (PMID 33457130, 2020). "Hence, serum BDNF levels can be an effective and helpful tool for evaluating diabetic retinopathy." (PMID 33457130, 2020). "BDNF is an essential neurotrophin that supports the function and survival of RGC, and is considered a possible treatment to prevent diabetic retinopathy-induced neuroretinal damage." (PMID 35223834, 2022). "The aim of this study is to review the documented reports on the role of BDNF and VEGF in pathogenesis and control of diabetic retinopathy and suggesting a relationship between these two factors." (PMID 32509339, 2020). "However, there is a lack of local data regarding the variation of BDNF levels among diabetic patients with progressive grades of diabetic retinopathy; hence, it remained undiscovered." (PMID 33457130, 2020).
Intellectual disability (24 papers, 2010 to 2025). "Identifying CaMKIV/EGR3/BDNF pathway in the hippocampal neurons in the context of CH will benefit the drug development of intellectual disability caused by CH." (PMID 36473844, 2022). "The observation further heightens the doubts regarding the efficacy of BDNF levels as a diagnostic tool for ASD since BDNF levels tend to be higher in children with mental retardation (MR), as observed by Nelson el al." (PMID 33060610, 2020). "Peripheral BDNF level is associated with attention deficit and intellectual disability in preschool children." (PMID 31514272, 2019). "There are some reports of an association between BDNF and intellectual disability and of a general inverse correlation with intelligence in children." (PMID 27200107, 2016). "Finally, genetic studies have linked specific BDNF polymorphism to altered cognitive performance and attentional deficits, highlighting a potential genetic contribution to the pathophysiology of intellectual disability." (PMID 40943255, 2025). "We analyzed four functional polymorphisms (rs25531, 5-HTTLPR, VNTR, rs3813034) of the SLC6A4 gene and one functional polymorphism (Val66 Met) of the BDNF gene in 98 patients with non-syndromic mental deficiency (NS-MD) and in an ethnically matched control population of 251 individuals." (PMID 20175892, 2010). "However, blood BDNF level alone may not provide a sufficiently specific test, since other causes of mental retardation also can increase BDNF levels in blood." (PMID 25182223, 2014). "The aim of the current paper is to determine whether particular alleles or genotypes of two crucial genes of these systems, the serotonin transporter gene (SLC6A4) and the brain-derived neurotrophic factor gene (BDNF), are associated with mental deficiency (MD)." (PMID 20175892, 2010). "On the contrary, increased BDNF levels have been detected in the blood of patients affected by intellectual disability (ID)." (PMID 37108250, 2023). "Serum levels of BDNF are altered in children with intellectual disability and ASD and also in children with other neurodevelopmental disorders, even in the absence of ASD52." (PMID 33060610, 2020). "Since the positive effect of exercise was paralleled by increased BDNF expression in trisomic mice, we investigated the effectiveness of a BDNF-mimetic treatment with 7,8-dihydroxyflavone at alleviating intellectual disabilities in the DS model." (PMID 29203796, 2017). "Conversely, another study suggests that dysregulation of BDNF contributes to the development of intellectual disability, and BDNF levels could serve as an early biomarker for identifying such disabilities." (PMID 38075212, 2023). "Our results suggest that high peripheral BDNF may be negatively correlated with intelligence, behavioral problems and clinical symptoms of neuro-developmental disorders such as intellectual disability in preschool children." (PMID 27200107, 2016). "They suggested that BDNF dysregulation may play a role in the development of intellectual disability and that BDNF levels may be an early biomarker for identification of intellectual disability." (PMID 27200107, 2016). "Our results show that BDNF may play a role in intelligence, attention and clinical symptoms of preschool children with neuro-developmental disorders such as intellectual disability and ADHD." (PMID 27200107, 2016). "Furthermore, despite the scarcity of studies, BDNF levels apparently cannot differentiate ASD from cases of intellectual disability without ASD52,61." (PMID 33060610, 2020). "These authors noted that BDNF concentrations were higher in children with ASD and in those with mental retardation without ASD than in control children." (PMID 33060610, 2020).
Seizure (24 papers, 2007 to 2025). A seizure is an intermittent abnormality of nervous system physiology characterized by a transient occurrence of signs and/or symptoms due to abnormal excessive or synchronous neuronal activity in the brain. "On the other hand, BDNF is known to have a protective role against excitotoxicity-mediated PTZ-induced seizure, and microglia have been shown to be activated following PTZ-induced chronic epilepsy." (PMID 39273208, 2024). "In patients with a TLE duration of less than 5 years, the BDNF concentration was higher compared with patients with a duration of epileptic seizures in the range of 10–20 years (30.4 [20.8; 30.4] ng/mL vs. 23.8 [19.8; 27.3] ng/mL), p = 0.025 by median test." (PMID 36677008, 2023). "On the other hand, valproic acid, a commonly used antiepileptic drug, rebalances TrkB and BDNF brain levels in Bassoon mutant mice and reduces epileptic seizures." (PMID 24278214, 2013). "A case-control study on 12 patients with psychogenic non-epileptic seizure (PNES), 15 patients with an epileptic seizure, and 17 healthy controls revealed that BDNF level serum was reduced in patients with epileptic seizure compared to other patients and healthy controls." (PMID 38006577, 2024). "The underlying cause for the reduction of BDNF after acute epileptic seizure is not fully elucidated." (PMID 38006577, 2024). "On the other hand, BDNF may exert a beneficial effect against the progression of epileptic seizures by enhancing the inhibitory GABAergic neurotransmission." (PMID 37737447, 2023). "Histone hyperacetylation in the BDNF (Brain-Derived Neurotrophic Factor) gene, which increases brain-derived neurotrophic factor expression, occurs after an epileptic seizure and is thought to be a neuroprotective mechanism that VPA may enhance or prolong." (PMID 36677060, 2023). "A case–control study on 12 patients with psychogenic non‐epileptic seizure (PNES), 15 patients with an epileptic seizure and 17 healthy controls revealed that BDNF level serum was reduced in patients with epileptic seizure as compared to other patients and healthy controls." (PMID 37737447, 2023). "Epileptic seizures may change the expression levels of both BDNF mRNA and protein in hippocampal neurons." (PMID 30524358, 2018). "Thus, we propose that adult patients with more severe focal motor seizures may have lower serum levels of BDNF." (PMID 30524358, 2018).